FOXM1 (forkhead box M1)
Diseases named in the same sentence as FOXM1 in open-access papers (continued):
Sharing a sentence is not in itself a finding about the gene and the disease.
cancer (continued). "This member of the Forkhead family regulates the expression of a large set of G2/M specific genes, and aberrant FOXM1 upregulation has been shown to be a key driver in cancer progression." (PMID 34646365, 2021). "Previous studies have indicated that FOXM1 promotes aerobic glycolysis in some cancers by directly targeting metabolic enzymes at the transcriptional level." (PMID 34740322, 2021). "FOXM1 has been studied mainly in cancer cells, including transformed human keratinocytes, where it drives G2/M transition." (PMID 33947848, 2021). "The meaning of our study is to provide more potential targets for the treatment of FoxM1-driven cancers." (PMID 33526768, 2021). "Given their numerous molecular links, it is likely that disruption of FOXM1 signaling accounts for, at least in part, the activity of PLK1i in cancer." (PMID 34205406, 2021). "New data on FOXM1 up‐regulation frequency, aetiology and outcomes in human cancers have been defined from 33 TCGA‐derived cancers." (PMID 33373169, 2021). "FOXM1, E2F1, and WEE1 have been implicated in the pathogenesis of human cancers, yet their roles remain vague in STS." (PMID 33564073, 2021). "Fork-head box protein M1 (FoxM1) is a transcriptional factor which plays critical roles in cancer development and progression." (PMID 33526768, 2021). "As most of the studies were performed in human cancer cells, the exact roles of FOXM1 in DDR in ESCs or during reprogramming to iPSCs are yet to be investigated." (PMID 34680943, 2021). "The updated data regarding the frequency, etiology, and outcomes of the forkhead box protein M1 (FOXM1) upregulation in human cancers were defined among 33 cancer types derived from TCGA databases." (PMID 33833994, 2021). "Overexpression of FOXM1 has been detected in multiple cancer types, suggesting that FOXM1 is essential for tumorigenesis." (PMID 34252882, 2021). "FOXM1 regulates all the hallmarks of cancer, including proliferation, mitosis, EMT, invasion, and metastasis." (PMID 33466512, 2021). "We further show that ZMYND8 functions as a scaffold protein that is critical for mediating the EZH2 recruitment of FOXM1 and the expression of cancer migration and invasion genes transactivated by the EZH2-FOXM1 complex." (PMID 33593912, 2021). "Sensitization of resistant cells to chemotherapy, especially to DNA-damaging drugs, is currently the most studied effect of FOXM1 depletion in cancer." (PMID 34262016, 2021). "Remarkably, and consistent with its function in a myriad of oncogenic phenotypes, FOXM1 has been reported as the top gene expression biomarker for poor prognosis in a pan-cancer analysis consisting of >18,000 tumors from 39 distinct malignancies." (PMID 34205406, 2021). "Consistent with the oncogenic role of FOXM1 in other cancers, the effective depletion of FOXM1 by either gene-specific shRNA inhibited the growth of MCF7 and T47D cells and impaired their clonogenic capacity." (PMID 34425866, 2021). "FOXM1, referred to as FOXM1B probably and FOXM1C in most cases, has been identified to be strongly upregulated in almost all types of tumors and as a major predictor for cancer prognosis by gene landscape analysis." (PMID 33314660, 2021). "Studies in other cancer types have identified well-known oncogenic transcription factors that bind to the FOXM1 promoter and induces its transcription: Gli1 and Gli2 in the sonic hedgehog (Shh) pathway, c-Myc, STAT3, and Twist1." (PMID 34205406, 2021). "Aberrant FOXM1 overexpression is found in most human cancers and is a major adverse prognostic marker." (PMID 34035233, 2021).
cancer (continued). "In cervical carcinogenesis, the expression of miR-197 was down-regulated in cancer tissues and cell lines, and overexpression of miR-197 inhibited growth and metastasis of cancer cells by directly targeting FOXM1." (PMID 32880393, 2020). "In epithelial ovarian cancer, FOXM1 promotes reprogramming of glucose metabolism in cancer cells via activation of HK-2 and GLUT1 transcription." (PMID 32489324, 2020). "FOXM1 promoted the proliferation and maintenance of breast, hepatocellular, pancreatic, and lung CSCs, and FOXM1 depletion repressed the stemness of these cancer cells." (PMID 31296961, 2020). "Further, several studies in cancer cells and chemoresistant patients have shown that FOXM1 regulation can improve the efficacy of cisplatin and paclitaxel." (PMID 33255409, 2020). "FOXM1 is known as a master regulator of cell proliferation, self-renewal, and tumorigenesis in various cancer cells." (PMID 32629770, 2020). "FOXM1 is regarded as an oncogene due to its contribution in tumor initiation and progression whose expression has been shown to be elevated in various cancers." (PMID 33680951, 2020). "FOXM1 affects the abnormal functions of cancer cells, including proliferation, cell cycle progression, apoptosis, angiogenesis, and DNA damage repair." (PMID 32486251, 2020). "Considering that EMT also plays a crucial role in chemoresistance of cancers, we further examined the effect of Snail on FOXM1-mediated expression of multidrug-resistance protein P-gp." (PMID 33291076, 2020). "The top activated transcriptional regulators were CENPA, FOXM1, TCF24, and MYBL2, which were linked to 875, 845, 843, and 840 cancer-specific enhancer probes, respectively." (PMID 32925947, 2020). "Forkhead box M1 (FoxM1) is one of the substrates of APC/CCdh1 in several cancer cells and is a well-established regulatory transcriptional factor for cell cycle progression." (PMID 32152291, 2020). "Recently, it has been suggested that FOXM1-regulatory network is a critical predictor of poor prognosis in 18,000 cancer cases across 39 human malignancies." (PMID 33291076, 2020). "FOXM1 is detected in highly proliferative cells of regenerating tissues and is upregulated in many types of human cancers, contributing to tumor development." (PMID 33142744, 2020). "As predicted, a previous report showed that a FOXM1 inhibitor (FDI-6) effectively showed anti-cancer effects by downregulating FOXM1-activated genes through the interruption of the DNA binding activity of the FOXM1 protein in MCF-7 cells." (PMID 32858881, 2020). "In vitro and in vivo experiments have supported the anti-cancer activity of FoxM1 inhibitor thiostrepton (TST)." (PMID 31992359, 2020). "Recently EPS8 was shown as a novel interacting partner of FOXM1 which further established its role in enhanced cancer cell proliferation, migration and invasion." (PMID 33680951, 2020). "We further revealed that GLUT1 is transactivated by the transcription factor Forkhead box M1 (FOXM1) in different cancer types." (PMID 32174012, 2020). "Further activated transcription regulators, such as β-catenin, Foxm1, Irf1, Myc, Mitf, Tbx2 with a somewhat lower z-score did also point to cell cycle regulation, DNA damage and cancer development." (PMID 32419051, 2020). "FOXO3a and FOXM1 are two forkhead transcription factors with antagonistic roles in cancer progression." (PMID 31296961, 2020). "Several studies indicate that development of docetaxel resistance is associated with FOXM1upregulation, and can be reversed by the down-regulation of FOXM1 expression in some cancers." (PMID 33292277, 2020). "Siomycin a and Thiostrepton have been widely used across various cancer cell lines due to its specificity to inhibit FOXM1 by interacting with the DNA binding domain and preventing any auto feedback via NFRM loop." (PMID 33680951, 2020). "This kind of regulatory axis can partially explain the resistance mechanism mediated by FOXM1 that has been observed in several cancers." (PMID 32858881, 2020).
cancer (continued). "On the other hand, FoxM1 has an important role in cancer because its overexpression has been found to be related to poor prognosis in patients." (PMID 32042016, 2020). "Previous studies showed that FoxM1 is highly expressed in multiple human cancers such as glioblastoma, breast cancer, and colorectal cancer." (PMID 32429421, 2020). "FOXM1 is proved to regulate Wnt/β-catenin, a well-known carcinogenic pathway in cancers, by interacting with β-catenin and facilitating its nuclear import." (PMID 32513952, 2020). "For example, the upregulation of FOXM1 expression is an early event during cancer initiation, progression, invasion, metastasis, and drug resistance." (PMID 31968679, 2020). "While being a key cell cycle regulator, FOXM1 also plays a multifaceted role in cancer progression, stimulating cancer cell migration, invasion, angiogenesis, stem cell self-renewal and therapeutic resistance." (PMID 32961773, 2020). "Among the mechanical reasons, previous studies showed that upregulation of FOXM1 induced cisplatin resistance in several cancer cells." (PMID 33053721, 2020). "Their analysis also revealed a correlation between aneuploidy and FOXM1 expression in TCGA pan-cancer aneuploidy clusters." (PMID 33680951, 2020). "FOXM1 confers resistance in cancer cells by increasing DNA damage repair; thus, the drugs targeting FOXM1 can prove promising results in inducing cell death in resistant tumor cells." (PMID 32679860, 2020). "The thiazole antibiotic Siomycin A, a known FOXM1 inhibitor in human cancer cells, significantly inhibited colony-forming ability and induced apoptosis of MV4-11, THP-1, and NOMO-1 but not that of K-562, Kasumi-3, HL-60, and U-937." (PMID 32066721, 2020). "Elevated cellular levels of FOXM1 in tumors have been strongly correlated with poor prognosis for cancer patients." (PMID 32365487, 2020). "We also investigated the pathway through which FOXM1 acts to interfere with anticancer drug therapy and the mechanism of cancer recurrence." (PMID 32486251, 2020). "FOXM1, a member of the forkhead box family of proteins, is involved in the regulation of numerous pathways that promote cancer." (PMID 31714026, 2020). "FOXM1 is overexpressed in most cancers and is also known to have implications in all hallmarks of cancer, primarily based on its ability to transcriptionally activate several downstream effectors." (PMID 33680951, 2020). "Recent studies indicate FOXM1 is commonly overexpressed in many kinds of cancers, including PCa, and its expression is highly correlated with cancer proliferation and metastasis." (PMID 33292277, 2020). "Because FOXM1 overexpression has been reported in cisplatin-resistant cancer cells, we next used qPCR to investigate the expression of FOXM1 mRNA in both the parental and cisplatin-resistant cell lines after 6 h treatment with cisplatin and/or paclitaxel." (PMID 33255409, 2020). "Several studies have reported on the role of FOXM1 in the proliferation of cancer cells and the development of anticancer drug resistance." (PMID 32629770, 2020). "The importance of FOXM1 in the development of stem cell-like properties has been well defined in various cancer types." (PMID 31296961, 2020). "FOXM1 is also closely tied to cancer cell stem cell properties such as cell proliferation, self-renewal, and tumorigenesis." (PMID 32210076, 2020). "Frequent amplification of FOXM1 was seen in various cancers among which testicular germ cell tumor had the maximum." (PMID 33680951, 2020). "As the review progresses the readers would obtain a clear view on multiple facets of FOXM1 in cancer and its impact on the homeostasis with special emphasis on the regulatory aspect of FOXM1 in cellular transformation." (PMID 33680951, 2020). "We recently identified and characterized novel FOXM1 inhibitory compounds, and demonstrated their beneficial role in suppressing cancer cell proliferation and tumor growth through cell cycle blockade and the induction of apoptosis." (PMID 32961773, 2020).
cancer (continued). "Abnormal upregulation of FOXM1 is involved in the oncogenesis of the majority of solid human cancers." (PMID 32742195, 2020). "Thiostrepton (TST), a cyclic oligopeptide antibiotic FOXM1 inhibitor, has been shown to enhance cancer cell chemo-sensitization significantly, leading to reduced proliferation." (PMID 33292277, 2020). "Currently, several FOXM1 inhibitors, including FDI-6 and RCM-1, have shown anti-cancer effects through the inhibition of FOXM1 in vitro." (PMID 32858881, 2020). "It has been found that FOXM1 depletion sensitizes the cells to premature senescence thus slowing down cancer progression." (PMID 33680951, 2020). "Alteration in Hh signaling, thereby the expression of FOXM1 has been evident from reports on various cancers." (PMID 33680951, 2020). "Overexpression of FOXM1 can promote cell migration and invasion, and induce premetastatic niche at the distal organ of metastasis in cancer cells." (PMID 33291076, 2020). "Having now identified these as key regulators in LUAD, we sought to determine if different enhancers are linked to FOXM1 and MYBL2 in the two cancer types." (PMID 32925947, 2020). "In this study, we demonstrated that a pseudogene, PTTG3P, was positively correlated with tumor aggressiveness and promoted cancer progression via a PTTG3P/miR-132/212-3p/FoxM1 feedback loop." (PMID 33298873, 2020). "To date, many studies have documented that FOXM1 is a key regulator of cancer cell proliferation, DNA damage repair, cancer drug resistance, metastasis and invasion." (PMID 32372224, 2020). "The cell lines of 3 cancer types had a strong (R>0.66) and another 3 had a moderate (0.65>R>0.35) positive correlation between FOXM1 expression and a marker for replication stress." (PMID 33253193, 2020). "In the ERα-positive cancer cell line, FOXM1 simultaneously occupies the same genomic position with the estrogen receptor in an ERα-dependent manner." (PMID 32858881, 2020). "Mammalian transcription factor forkhead box M1 (FOXM1) is associated with cell proliferation and can be upregulated in cancer." (PMID 33255409, 2020). "FOXM1 expression is elevated in many types of cancer, where it is involved in tumor initiation, progression, invasion, metastasis, angiogenesis, and drug resistance." (PMID 32976773, 2020). "Although several inhibitors have been developed for targeting FOXM1 at multiple levels, specific delivery to cancer cells is the need of the hour to avoid disbalance of cellular homeostasis." (PMID 33680951, 2020). "Inhibition of FOXM1 activity is attractive for cancer therapy and several small molecule inhibitors were identified to suppress FOXM1 through multiple mechanisms." (PMID 32723329, 2020). "We earlier showed FOXM1 to play a key role in promoting endocrine resistance in hormone receptor-positive breast cancers by expanding the cancer stem-like cell population." (PMID 32961773, 2020). "Overexpression of FOXM1 has been observed in a variety of cancer types, indicating that FOXM1 plays essential roles in carcinogenesis." (PMID 33311446, 2020). "Reducing FOXM1 expression can lead to decreased cancer progression and an increased sensitivity to chemotherapy in many tumors." (PMID 33292277, 2020). "As an important member of Forkhead Box transcription factor family, it has been postulated that the function of FOXM1 is determined by its capacity to transactivate various target genes that are involved in multiple stages of cancer development." (PMID 33291076, 2020). "FOXM1 is an oncogenic transcription factor known to play an important role in anticancer drug resistance, and it promotes cancer progression." (PMID 33255409, 2020). "FOXM1 contributes to multiple cancers by promoting cellular proliferation and tumor initiation via β-catenin and cyclin D1." (PMID 32391055, 2020). "Meanwhile, the expression of FOXM1 was stimulated in RCC cancer tissues with the decrease in miRNA‐132 expression." (PMID 31625200, 2020).
cancer (continued). "FOXM1 is one of the major transcription factors altered in cancer by virtue of altered signal transduction pathways." (PMID 33680951, 2020). "Our data revealed that co-treatment with RAME and cisplatin was effective against cisplatin-resistant cancer cells by inhibiting the expression of FOXM1 and its target genes, ultimately inducing apoptosis in these cells." (PMID 33053721, 2020). "As a master regulator of the cell cycle, FOXM1 is highly likely to be an important transcription factor for various types of cancer." (PMID 32858881, 2020). "Inhibition of FOXM1 effectively reduced cancer stemness characteristic in enzalutamide-resistant CRPC." (PMID 32629770, 2020). "Previously, studies have argued that besides cell cycle, FOXM1 can also influence many other cancer-related processes, like cellular growth, invasion, angiogenesis, metastasis, and EMT7–9." (PMID 32513952, 2020). "Thiostrepton (TST), a specific inhibitor for FoxM1, shows anti-cancer activity in many human cancers." (PMID 31992359, 2020). "Compounds such as β-lapachone and 5-fluorouracil have been shown to induce cancer apoptosis through the activation of FOXOs and its target FOXM1." (PMID 32372224, 2020). "FOXM1 functions as a transcription factor and its upregulation has been reported in numerous cancers." (PMID 32629770, 2020). "This study explores the role of FOXM1 in PCa docetaxel resistance and its association with kinesin family member 20 A (KIF20A), which is known to promote therapeutic resistance in some cancers." (PMID 33292277, 2020). "Several studies indicate KIF20A is transcriptionally regulated by FOXM1 in certain cancer cells, and that their expression is consistently elevated after treatment with paclitaxel." (PMID 33292277, 2020). "Among the activated transcriptional regulators identified, CENPA, FOXM1, and MYBL2 were linked to numerous cancer-specific enhancers." (PMID 32925947, 2020). "ALKBH5 mediated the cancer progression 3 and stemness behavior of GSCs through demethylation of the transcription factor FOXM1 nascent transcripts, thus increasing FOXM1 expression." (PMID 32194861, 2020). "FOXM1 is an essential component of Akt signaling, which functions both in the context of tumor stroma and cancer cells to promote tumorigenesis." (PMID 32660466, 2020). "Of the transcriptional regulators activated in LUAD, CENPA, FOXM1, and MYBL2 were linked to the activation of hundreds of cancer-specific enhancers." (PMID 32925947, 2020). "Forkhead box M1 (FOXM1) is an oncogenic transcription factor that is always upregulated in various cancers including ccRCC." (PMID 32595418, 2020). "Emerging evidence suggests that aberrant activation of FOXM1 signaling stimulates tumorigenesis and tumor aggressiveness in various cancer cells by increasing drug resistance and migration/invasion." (PMID 32858881, 2020). "FOXM1 is a typical transcription factor related to cell proliferation and involved in cancer growth." (PMID 33124191, 2020). "According to a new pan-cancer meta-examination of nearly 18,000 gene expression signatures, FOXM1 is recognized as a significant predictor of detrimental outcomes in 39 hematologic and solid malignancies, including MM." (PMID 32679860, 2020). "The transcription factor FOXM1 is involved in many crucial biological processes and specifically related to cell cycle progression and cancer evolution." (PMID 32603365, 2020). "FOXM1 also increases the population, proliferation, and motility of cancer stem cells, which make cancers tolerant to drugs like cisplatin." (PMID 33053721, 2020). "In contrast, aberrant expression of STAT3, HIF1 α, NF-κB, AP-1 and FoxM1 are often observed in different types of cancers." (PMID 33053689, 2020). "FOXM1 is a transcription factor widely expressed in pre-malignant lesions and cancer, and is included in a chromosomal instability signature correlating with functional aneuploidy and highly predictive for clinical outcomes." (PMID 33253193, 2020).